MTOR (mechanistic target of rapamycin kinase)
Diseases named in the same sentence as MTOR in open-access papers (continued):
Sharing a sentence is not in itself a finding about the gene and the disease.
tumor (continued). "To date, human trials involving rapalogues have been performed in patients with advanced disease, and with no selection to identify tumours that might be particularly dependent upon mTOR signalling." (PMID 24717934, 2014). "Thus, in hyperinsulinemic individuals, the continuous activity of insulin in non-resistant tissues promotes the activation of the mTOR system, thereby favoring cellular proliferation and tumor development." (PMID 25533006, 2014). "Only 20% of the tumour samples were scored positive for p-mTOR expression; the adjacent non-tumour urothelium (apparently normal or hyperplasic) was immunostained in 36% of the tissue sections, although only the superficial layers, including umbrella cells, were stained." (PMID 25202348, 2014). "In addition to mTOR activation, the miR-634-induced up-regulation of ERK1/2 activity could also promote a partial chemoresistant phenotype in tumor cells." (PMID 24705102, 2013). "One limitation of the study is that the examined tissues are post-chemotherapy resected tumors and that activation of mTOR pathway could be due to chemotherapy treatment rather than by the tumor-specific genetic or epigenetic alterations." (PMID 23922674, 2013). "However, blocking mTOR activity with rapamycin (the prototype mTOR inhibitor) or rapamycin analogs inadvertently activates the Akt-signaling pathway through an IGF-1R-dependent mechanism, which mitigates the anti-tumor effects of the mTOR inhibitors." (PMID 23548153, 2013). "As reported, metformin activated AMP-activated protein kinase (AMPK) through phosphorylation; however its inhibitory effect on the mammalian target of rapamycin (mTOR) pathway did not necessarily correlate with its anti-tumor activity toward EpCAM+ tumor-initiating HCC cells." (PMID 23922888, 2013). "Different lesions upregulating the mTOR signaling pathway may have non-identical therapeutic implications, however, emphasizing that prediction of effective tumor targeting may come to involve more than a one-off genetic predictive assay." (PMID 24377088, 2013). "However, in this study, we demonstrated that this new drug acts as a multitarget kinase inhibitor that may directly block tumor growth by inhibiting several other kinases such as ERK, Akt, and mTOR in human RCC lines." (PMID 24133625, 2013). "Therefore, targeting mTOR and UPR could provide another opportunity to enhance selective tumor cell kill." (PMID 24152759, 2013). "When not diffusely located within tumour cells, p-mTOR was present in luminal epithelial cells." (PMID 23587222, 2013). "However, the noted ATP-P2X7-induced blockade of mTOR and PI3K/AKT signaling associated with tumor cell death is not regulated via pannexin- or connexin type channels nor by varied levels of mitochondrial ROS production, as previously reported in prior studies." (PMID 23565201, 2013). "Thus, co-targeting the PI3K/Akt/mTOR pathway and its upstream signal, IGF-1R may prove to have synergistic anti-tumor effects and is worthy of further investigation." (PMID 23663564, 2013). "Unlike normal cells, tumor cells with an elevated mTOR activity were more sensitive to inhibition of mTOR or glycolysis, and dual suppression of mTOR and glycolysis acted synergistically to inhibit proliferation and tumor growth." (PMID 22680924, 2012). "Our results suggest that tumours that do not involve activation of the mTOR pathway may not benefit from everolimus treatment." (PMID 22343617, 2012). "In this regard, we would predict that mTOR inhibition in the absence of proximal PI3K blockade might also have directs effects on inhibiting tumor growth but would serve to limit development of anti-tumor immunity." (PMID 23087689, 2012).
tumor (continued). "Furthermore, the levels of expression and activation of the Akt and mTOR pathways have not been analyzed extensively in irradiated tumours long after treatment." (PMID 22607554, 2012). "Further studies employing SFK inhibitors, as single agents or in combination with mTOR inhibitors or other treatments, in animal models of GEP ETs could further support the relevance of SFKs in this tumor type, and eventually set the ground for clinical trials." (PMID 23344019, 2012). "Importantly, the correlation between 5p13 copy number and increased phosphorylation of the p70 S6 kinase mTOR substrate in NSCLC tumor specimens links GOLPH3 function to mTOR activation and indicates that GOLPH3 tumorigenesis may be mediated by mTOR signaling." (PMID 22905766, 2012). "Since tumor size is used directly in the calculation of PFS, the primary trial end point, this model may provide improved understanding of the everolimus dose–response relationship relative to methods that utilize measures of mTOR pathway inhibition." (PMID 22824201, 2012). "Thus, the combination therapy or a dual-specificity agent that targets both mTOR function and AKT activation may improve anti-tumour activity." (PMID 22408430, 2012). "Assuming these results, targeted therapies for mTOR may be used in combination therapy, aiming to induce a cytotoxic rather than a cytostatic response and subsequent tumour regression." (PMID 22408430, 2012). "The tumor microenviroment can secrete growth factors such as hepatocyte growth factor (HGF) which results in activation of the HGF receptor MET and subsequent downstream Raf/MEK/ERK and PI3K/PTEN/Akt/mTOR signaling which results in resistance to the small molecule inhibitors." (PMID 23085539, 2012). "In patient 1, upregulation of p-Akt and p-mTOR in the tumor that relapsed after initial response to IGF1R antibody might explain the resistance that developed, and the subsequent response to combined IGF1R plus mTOR inhibitor therapy." (PMID 21494688, 2011). "Therefore, the effects of mTOR inhibition on DCs do not explain the enhanced anti-tumour immunity seen in our models." (PMID 21285988, 2011). "This may be due to the fact that mTOR monotherapies only abrogate the mTORC1 complex and not mTORC2, which is involved in tumour cell invasion." (PMID 20515495, 2010). "Preoperative chemotherapy had no influence on p-mTOR and p-p70s6K tumour expression." (PMID 20683448, 2010). "However, we did not observe a clinically relevant anti-tumor effect with the mTOR inhibitor temsirolimus or with the everolimus + erlotinib combination." (PMID 20630061, 2010). "Indeed, phosphorylated mTOR has been generally found to be expressed in relatively low numbers of tumours, and several studies make no reference to tumour mTOR expression when assessing the effect of rapamycin and or its analogues." (PMID 19401700, 2009). "Moreover, S9 induced rapid apoptosis in tumor cell, which might reflect a synergistic cooperation between blockade of both PI3-Akt-mTOR signaling and tubulin cytoskeleton." (PMID 19293927, 2009). "Importantly, in normal SVZ cells, chemically HIF-1α stabilization was only transiently inducing REDD1 upregulation and Akt/mTOR pathway was not inhibited, unlike in tumor cells, following BMP2 treatment, and Akt and Stat3 were eventually upregulated." (PMID 19587783, 2009). "Such cooperation between blockade of PI3-Akt-mTOR signaling and tubulin cytoskeleton contributes to its anti-proliferative activity observed in vitro against a panel of tumor cells including MDR tumor cells and in vivo antitumor activity in mice bearing human tumor xenografts." (PMID 19293927, 2009). "Furthermore, changes in phosphorylation of molecules downstream of mTOR do not necessarily correspond with tumour response." (PMID 19436299, 2009).
tumor (continued). "Only substrates activated by nuclear p-mTOR may not be adequate to promote tumour growth because nuclear p-mTOR was found more frequently in early-stage disease." (PMID 19223902, 2009). "Notably, normal SVZ-derived cells underwent mTOR but not analogous Akt, Stat3 and p70S6K activation following high oxygen acute exposure, suggesting differences in oxygen sensitivity between tumour and normal cells." (PMID 19587783, 2009). "In contrast, pS6 was the only component of the activated mTOR pathway that significantly predicted relapse where the mean disease-free survival in patients whose primary tumours expressed pS6 was 3.77 vs 6.11 in those patients whose tumours did not (P=0.0096)." (PMID 18283322, 2008). "Other studies of non-RCC primary tumours have frequently identified mTOR activation." (PMID 15956968, 2005). "Furthermore, transient inhibition of mTOR between day 30 and day 60 profoundly impacted end-stage tumour formation, compromising the ability of Ctnnb1ex3/WT;R26LSL-MYC hepatocytes to form tumours, resulting in a significant reduction in tumour number and an extension in survival." (PMID 41261129, 2026). "In addition, GAS5 controls critical signaling pathways like PI3K/AKT/mTOR, which are fundamental to cancer progression.Furthermore, GAS5 can enhance radiosensitivity by modulating DNA damage responses or influencing the cellular process in the tumor microenvironment." (PMID 39958058, 2025). "In addition to the mTOR role in glycolysis, it has been reported that Phosphoinositide 3-kinases (PI3K)/Protein kinase B (Akt)/mTOR contributes to shaping the interaction between TILs and tumor cells, suggesting the key role of mTOR in determining tumor growth, progression, and drug resistance." (PMID 40872545, 2025). "In addition, mTOR kinase inhibitors release negative feedback on PI3K/Akt in tumor cells." (PMID 40640525, 2025). "The DDIT4-mediated inhibition of the PI3K-Akt/mTOR pathway may modulate the TIME through multiple mechanisms, and a comprehensive understanding of these regulatory pathways could provide valuable insights for optimizing the precision and efficacy of tumor immunotherapy." (PMID 40900790, 2025). "In addition, signaling pathways such as canonical or non-canonical ER signaling and tumor cell survival pathways such as RAS, PI3K, AKT, and mTOR may be susceptible to natural products." (PMID 40141171, 2025). "In addition, mTOR acts as a center of metabolic regulation, activating downstream signaling pathways (e.g. PI3K-AKT) via the mTORC1 and mTORC2 complexes, driving metabolic reprogramming of tumor cells in terms of glucose uptake, essential amino acid utilization and lipid synthesis." (PMID 40860199, 2025). "Furthermore, we verified our findings through immunohistochemical sections of tumor tissue, which indicated that TMEM45A knockdown could suppress the levels of p-AKT and p-mTOR, and the use of SC79 could attenuate the inhibitory effect of TMEM45A knockdown on the pathway." (PMID 39910045, 2025). "The inhibition of the PI3K/AKT/mTOR pathway not only restores apoptotic signaling in tumor cells but may also promote the release of apoptosis-related signaling molecules, such as DAMPs and HMGB1, and pro-inflammatory cytokines, such as IL-12 and IFN-γ, which activate anti-tumor immune responses." (PMID 39972480, 2025). "Similarly, combining KRAS blockade with MEKi, PI3K/MTOR inhibitors, or other agents may achieve greater degrees of tumor suppression without rebound activation of other pathways." (PMID 40615690, 2025). "In the meantime, in vitro investigations revealed that FBXW7 may serve as a tumor suppressor gene in CRC, inhibiting proliferation and metastasis of CRC cells via two different mechanisms: reduction in arginine production through metabolic reprogramming and direct down-regulation of mToR signaling." (PMID 39823500, 2025).
tumor (continued). "Additionally, the EGFR/PI3K/AKT/mTOR pathway directs macrophage polarization towards the M2 phenotype, which secretes growth factors such as EGF, platelet-derived growth factor (PDGF), and transforming growth factor (TGF)-β, favoring tumor cell proliferation and survival." (PMID 38191508, 2024). "Consistently, the activation of the Akt/mTOR pathway decreased with ALO treatment in NSCLC cells in vitro and mouse tumor models in vivo, whereas the levels of Beclin‐1 and ATG7 increased, indicating that ALO may promote autophagosome formation by interfering with the Akt/mTOR pathway." (PMID 39166458, 2024). "These different approaches demonstrated that pan-PI3K/mTOR inhibition by gedatolisib generally exerted more potent and efficacious anti-proliferative/cytotoxic effects than single-node PAM inhibitors, regardless of the tumor cells’ PAM pathway mutational status." (PMID 38839777, 2024). "Moreover, the mechanism of mTOR resistance in each tumor type has not been elucidated yet." (PMID 38846332, 2024). "Interestingly, a tumor suppressor miR-3188 could induce its own expression by interacting with FOXO1 to form a mTOR/PI3K/AKT/c-JUN negative feedback loop, thereby increasing the sensitivity of NPC cells to 5-FU." (PMID 38254110, 2024). "Moreover, mTOR (mammalian target of rapamycin), a downstream protein kinase of the PI3K/AKT signaling pathway, plays an important role in physiological and pathological processes, such as cell proliferation, differentiation, autophagy, protein synthesis, and tumor growth." (PMID 39585848, 2024). "TNF-alpha signaling via NF-kB, IL6/JAK/STAT3 signaling, PI3K/AKT/mTOR signaling, MYC targets v2, TGF-beta signaling, and Kras signaling were mostly negatively correlated with LRRC3B expression, consistent with silencing of LRRC3B in tumor tissue, which may result in carcinogenesis." (PMID 36798137, 2023). "Additionally, multiple factors including drugs, proteins, RNA, and genes either positively or negatively regulate tumor cells proliferation, invasion, and apoptosis in OS by affecting the signaling pathways JAK/STAT3, Hippo, Wnt/β‐catenin, PD‐1/PD‐L1, Notch, MAPK, PI3K/AKT/mTOR, NF‐κB, and others." (PMID 37441462, 2023). "Strikingly, the combinatorial treatment also showed activity against cells originating from refractory GCB and non-GCB DLBCL patients, indicating that dual mTOR and PI3Kβ/δ inhibition might represent a promising novel strategy to target tumor cells resistant to first-line therapy." (PMID 36352190, 2023). "However, rapamycin, an mTOR inhibitor, resulted in the reversal of enhanced anoikis and reduced ATP levels in GDH-knockout cells, suggesting that GDH may promote tumour metastasis through the activation of AMPK by CamKK2 and subsequent suppression of mTOR signalling." (PMID 37829798, 2023). "The role of STAT3 in GBM pathogenesis is still under debate, as it is unclear whether it is pro-oncogenic or tumor-suppressive, and recent reports suggest a feedback activation mechanism in STAT3, rather than inhibition, in response to the inhibition of the PI3K/Akt/mTOR signaling pathway." (PMID 38137388, 2023). "Furthermore, CAFs may also promote the proliferation of HPV+ve and negative tumour cells after cetuximab and mTOR inhibitor treatment." (PMID 36980527, 2023). "In addition, we also detected the protein expression of TRMT6 downstream pathway-related proteins in tumor tissues, and the results showed that overexpression of TRMT6 could increase the expressions of p-PI3K, p-AKT and p-mTOR, while interference with TRMT6 had the opposite effect." (PMID 36707905, 2023). "Moreover, we developed a three-tiered integrated risk stratification model incorporating mitotic count, density of Ki-67+ and CD163+ cells, and MTOR mutation to more accurately identify SFT patients of primary non-CNS and CNS SFTs with negative tumor margins (NTM) at high risk for tumor progression." (PMID 37980418, 2023).
tumor (continued). "In addition, adenosine monophosphate-activated protein kinase (AMPK)/mammalian target of Rapamycin (mTOR) 48 and signal transducer and activator of transcription 3 (STAT3) 49 signaling pathways have also been reported to mediate the regulation of FASN in tumor proliferation and metastasis." (PMID 37497413, 2023). "Defective autophagy induced by PI3K/AKT/mTOR signaling activation might have negative implications on the survival of rapidly proliferating tumor cells, so compensatory mechanisms might be activated to counterbalance the suppression of autophagy by mTOR activation." (PMID 37575061, 2023). "Besides, tumor weight was recorded and analyzed after dissection, the role of VSIG2 depletion in tumor weight was impaired after elevation of LAMTOR2 or supplement of mTOR activator, indicating that VSIG2 advanced PDAC progression through LAMTOR2-mediated mTOR activation." (PMID 37626304, 2023). "Additionally, recent research has shown that the mTOR, Raf/mitogen-activated protein kinase (MEK)/ERK, AMP-activated protein kinase (AMPK), nuclear factor kappa B (NF-κB), and Hedgehog signaling pathways are closely related to m6A modification, which mediates the regulation of tumor phenotypes." (PMID 36960074, 2023). "In addition, following PKM2 knockdown and overexpression, the expression levels of p-AMPK, p-mTOR, p-ULK1, and p-4E-BP1 proteins in Ad-apoptin treated tumor cells were analyzed by western blot to investigate the mechanism of apoptin effect on the energy metabolism of tumor cells." (PMID 36284386, 2022). "Another explanation may be that the mTOR pathway interacts with other compensatory pathways and thus may circumvent inhibition by everolimus by several negative feedback loops via the activation of other signaling pathways, such as MAPK signaling, for tumor proliferation." (PMID 35454843, 2022). "Although the oxidation of mTOR has not been reported in tumor cells, given the important role of ROS, mTOR signaling and autophagy in tumor progression, it is reasonable to presume that ROS might be involved in tumor progression by directly oxidizing mTOR to regulate autophagy." (PMID 36676047, 2022). "Observations from our data suggest that the patterns of tumor characteristics in relation to gene expression may not be consistent with the patterns of the phosphorylation of proteins through which the mTOR pathway responds to the extracellular environment, e.g., energy and amino acid influx." (PMID 35608730, 2022). "Since the AKT/mTOR pathway is known to play a central role in the regulation of cell lipid metabolism, we hypothesised that blocking ACLY will reduce lipid synthesis and subsequently prevent tumour cell resistance to TKI therapy, enhancing its antitumor efficacy." (PMID 36064336, 2022). "However, several factors including tumor heterogeneity, epigenetic regulation by miRNAs, synergistic effects of multiple signaling pathways such as Akt/PI3K, MAPK/ERK, NF-κB/IL-6, mTOR, Hedgehog, and somatostatin receptor have been shown to contribute to drug resistance in these tumor cells." (PMID 33805398, 2021). "In addition, epidermal growth factor receptor (EGFR), mammalian target of rapamycin (mTOR), vascular endothelial growth factor (VEGF), fibroblast growth factor (FGF) and their downstream pathways are triggered in PAs, thereby modulating tumor cell proliferation, migration and/or tumor angiogenesis." (PMID 35011868, 2021). "Importantly, mTOR exists in two different complexes: mTORC1, which is the target for rapamycin and its analogues, and mTORC2, which activates AKT, thereby promoting feedback tumor cell proliferation and the development of resistance to mTORC1 inhibitors (mTORC1i)." (PMID 34944946, 2021). "However, recent studies have demonstrated that the mTOR blockade has surprising immunostimulatory effects by enhancing the generation of memory precursor effector cells that survive and differentiate into long-lived CD8+ memory cells, allowing better clearance of tumor cells." (PMID 35250965, 2021).